KL (klotho)
Diseases named in the same sentence as KL in open-access papers (continued):
Sharing a sentence is not in itself a finding about the gene and the disease.
diabetes (continued). "Targeting the FGF-Klotho endocrine axis plays a critical role in the pathophysiology of aging-related diseases, such as diabetes, cancer, arteriosclerosis, and chronic kidney disease, some of which are associated with obesity (e.g., arteriosclerosis, diabetes, osteoporosis)." (PMID 40007807, 2025). "Additionally, after adjusting for confounding variables including smoking, gender, age, diabetes, alcohol consumption, and other covariates, a significant inverse association was observed between ABSI and Klotho protein levels." (PMID 40007807, 2025). "Furthermore, MR409 prevented the diabetes-mediated downregulation of the anti-aging protein Klotho and PPARγ expression." (PMID 40926987, 2025). "Third: Animal experiments and early exploratory studies suggest that exogenous supplementation of Klotho protein, Klotho-derived peptides, and up-regulation of endogenous Klotho by drugs or genetic engineering may improve diabetes-related organ damage." (PMID 41438297, 2025). "Moreover, circulating Klotho levels were analysed in the presence of other relevant cardiovascular comorbidities, such as diabetes mellitus (DM), hyperlipidaemia, hypertension, or previous IHD." (PMID 39815421, 2025). "The potential mechanism of Klotho in diabetes can be summarized as ‘ three pathways ‘." (PMID 41438297, 2025). "The clinical implication is that if exogenous Klotho supplementation or endogenous Klotho expression can be promoted in the early stage of diabetes, it is expected to protect podocytes before the occurrence of proteinuria, thereby delaying or even blocking the occurrence of DKD." (PMID 41438297, 2025). "The current research on Klotho in diabetes mainly focuses on the following three levels." (PMID 41438297, 2025). "Furthermore, gene therapies focusing on Klotho are being evaluated for therapeutic alternatives for conditions such as diabetes mellitus and neurodegenerative diseases such as epilepsy and Alzheimer's disease." (PMID 38213484, 2024). "This suggests that Klotho may be involved in the development and progression of diabetes-related vascular complications." (PMID 38672115, 2024). "We did not observe the interactions between Klotho and age, sex, physical activity, smoking, obesity, diabetes, hypertension and CKD stages for all-cause and cardiovascular mortality." (PMID 38409304, 2024). "After adjustment for age, sex, BMI, duration of diabetes, and HbA1c, urinary Klotho was significantly associated with UACR ≥ 3.0 mg/mmol in patients with T2D (OR = 0.96, 95% CI 0.93–0.9996 for each 10 ng/mmol of urinary Klotho, p = 0.048)." (PMID 38540101, 2024). "Hypertension, diabetes, and CHD are linked to oxidative stress and chronic inflammation, which could potentially suppress Klotho expression." (PMID 39723163, 2024). "Interestingly, other studies that enrolled patients with moderately impaired kidney function, mostly patients with diabetes (74%), reported positive correlations of serum Klotho with matrix calcium deposition in coronary biopsies." (PMID 37686263, 2023). "In addition, baicalin and curcumin have been found to regulate endogenous klotho expression by modulating klotho promoter methylation, which can alleviate diabetes or cyclosporin A-induced kidney injury in mice." (PMID 37143722, 2023). "Furthermore, the relationship between carbohydrate intake and serum Klotho levels was weakened in the context of diabetes." (PMID 37764740, 2023). "In the stratified analyses, age, sex, BMI and diabetes did not significantly modify the association between the carbohydrate energy percentage and serum Klotho levels (all p-interactions > 0.05)." (PMID 37764740, 2023). "Our findings reveal an interesting relationship between carbohydrate intake and Klotho levels, and this association seems to be more pronounced in males, non-obese individuals, and those under 60 years of age without diabetes." (PMID 37764740, 2023).
diabetes (continued). "Negative correlation between the levels of FGF19 and VEGF, and positive correlation between the levels of FGF19 and Soluble Klotho may suggest its possible involvement in the development of chronic complications of diabetes." (PMID 36927328, 2023). "In simpler terms, the levels of serum soluble klotho have a positive correlation with the estimated glomerular filtration rate (eGFR) and a negative correlation with urinary albumin, particularly in patients with diabetes." (PMID 37143722, 2023). "Although the cardio-renal protective effects of Klotho have been well established, the predictive capabilities of serum Klotho levels for diabetes remain largely unknown." (PMID 36440221, 2022). "Additionally, those in the lowest quartile of Klotho levels were more likely to have diabetes, hypertension, CHF, CHD, heart attack, and stroke." (PMID 35509269, 2022). "In summary, a nonlinear and positive association was found between serum Klotho levels and the prevalence of diabetes." (PMID 36440221, 2022). "The prevalence of diabetes increased with increasing quartiles of serum Klotho." (PMID 36440221, 2022). "Klotho has been demonstrated to exert therapeutic effects on diabetes and its complications." (PMID 36440221, 2022). "We hypothesize that Klotho therapy of diabetes will be helpful when normal plasma levels are restored." (PMID 35903083, 2022). "This explanation was consistent with the findings from another study that the serum levels of Klotho increased at the onset of diabetes as a potential compensatory mechanism in response to high glucose stimulation, while their levels recovered as diabetes progressed." (PMID 36440221, 2022). "Klotho expression declines with age, renal failure, diabetes and neurodegenerative disease." (PMID 35903083, 2022). "It indicated that klotho might be involved in developing diabetes during pregnancy and might be an important marker of GDM." (PMID 36325267, 2022). "In our study, loss of Klotho in the diabetic setting was restored in mice lacking C5aR1 expression or function in our long-term diabetes model of 24 weeks." (PMID 36434087, 2022). "The main strength of our study is the robust evidence on the association of serum Klotho levels with diabetes based on a nationally representative and noninstitutionalized US civilian population." (PMID 36440221, 2022). "We hypothesized that KL levels will be affected by diabetes duration and glycemic control in children with Type 1 diabetes, and KL levels could be regulated by miRNAs, specifically miR-192." (PMID 35992154, 2022). "miR-192 and/or KL levels are altered with severity and duration of diabetes and could serve as early biomarkers for DN." (PMID 35992154, 2022). "In general, compared with middle-aged and elderly individuals with lower plasma S-Klotho levels, people with higher plasma S-Klotho levels were more likely to be female, younger, and have hypertension, hyperuricemia, heart failure, coronary heart disease, stroke, and diabetes prevalence is lower." (PMID 36411464, 2022). "Given Klotho may also serve as a potential predictive marker for diabetes, future studies are needed to shed light on the explicit association of serum Klotho level with HbA1c and reveal the underlying mechanisms." (PMID 36440221, 2022). "Since Klotho is reported as an anti-aging gene and T2D has been considered by some as a condition of accelerated senescence, one would expect lower levels in patients with worse diabetes control." (PMID 35286490, 2022). "In summary, our study demonstrated that serum Klotho levels were nonlinearly and positively associated with the prevalence of diabetes in a nationally representative adult population." (PMID 36440221, 2022). "Klotho concentration may be considered as a prognostic factor in the development of chronic complications of diabetes." (PMID 34603200, 2021). "Serum levels of SIRT1 and Klotho in pre-diabetes were lower than in healthy controls and diabetics." (PMID 34670596, 2021).
diabetes (continued). "Additionally, no analyses on the effective dose of Klotho or the needed frequency of its administration were performed, which must be done before introducing Klotho as a promising agent in immunotherapy for diabetes and diabetic nephropathy." (PMID 33478014, 2021). "Significantly lower urine levels of Klotho may serve as an early biomarker of renal involvement in diabetes mellitus." (PMID 33478014, 2021). "Therefore, the current manuscript aims to characterize immunopathologies occurring in diabetes and diabetic nephropathy, and tries to match them with antiinflammatory actions of Klotho." (PMID 33478014, 2021). "Recombinant Klotho administration and Klotho overexpression may have immunotherapeutic potential for the treatment of both diabetes and diabetic nephropathy." (PMID 33478014, 2021). "The role of Klotho in these cells would be to contribute to an antiinflammatory process, present in young and healthy subjects but lowered together with senescence and in inflammatory disorders, such as rheumatoid arthritis, diabetes, and diabetic nephropathy." (PMID 33478014, 2021). "Negative correlation between the levels of HbA1c and soluble Klotho may suggest its possible involvement in the development of chronic complications of diabetes." (PMID 34603200, 2021). "Limited studies have examined the expression of SIRT1 and Klotho in pre-diabetes." (PMID 34670596, 2021). "In this study, our data showed that Klotho deficiency may cause loss of regulation in OGG1 expression and promote the generation of ROS and DNA damage, which eventually aggravated MtD in diabetes-induced podocytes." (PMID 33162804, 2020). "Moreover, our study focused on diabetes-induced DNA damage and found the relationship between Klotho and DNA damage in diabetes nephropathy (DN)." (PMID 33162804, 2020). "Noteworthily, our study found Klotho deficiency may aggravate podocyte MtD for the failure of regulating ROS-induced low expression of OGG1 and deteriorate 8-OHdG-induced DNA damage in diabetes." (PMID 33162804, 2020). "Interestingly, Klotho level was depleted in the pancreatic islets in patients with type 2 diabetes mellitus." (PMID 32319182, 2020). "Our results imply that Klotho deficiency may aggravate podocyte MtD by affecting ROS and 8-OHdG-induced DNA damage by affecting OOG1 in diabetes." (PMID 33162804, 2020). "Regarding the diabetes-stimulated mouse heart, an improvement of cardiac function and mitigation of cardiac oxidative stress, decreased cell death, and remodeling after the Klotho injection were observed." (PMID 30671457, 2018). "Growing evidence suggests that an increase in KL expression may be beneficial for age-related diseases such as arteriosclerosis and diabetes." (PMID 28657902, 2017). "Klotho, which is a kind of anti-aging protein, is involved in various pathologies, such as atherosclerosis, heart damage, hypertension, acute kidney injury, chronic kidney disease, diabetes mellitus, and even cancer." (PMID 28407763, 2017). "Moreover, vascular expression levels of Klotho were related with the incidence of diabetes mellitus and coronary artery disease." (PMID 26538295, 2016). "Therefore, Klotho is not only an early diagnostic marker, but also a promising therapeutic target for CKD and diabetes." (PMID 27668003, 2016). "Although it is necessary to interpret these data with caution, these findings suggest that Klotho may be involved in the pathogenesis of diabetes mellitus." (PMID 26538295, 2016). "Klotho deficiency, as part of Kidney Essence Deficiency, is widely present in CKD and diabetes and may play an important role in the development of metabolic bone disorder." (PMID 27668003, 2016). "Our results indicate that the polymorphic variability in Klotho gene may be a factor influencing tissue expression levels of this protein as well as in the incidence of diabetes mellitus, atherosclerotic vascular disease and coronary heart disease." (PMID 26538295, 2016).
diabetes (continued). "Low serum Klotho levels have been reported in patients with diabetes mellitus." (PMID 23431388, 2013). "Macrophages from the kidneys of mice with diabetes are deficient in growth/differentiation factor-15 (GDF-15), which is required for oxidative metabolism in M2-like macrophages, resulting in a decrease in Klotho, an antiaging single-pass membrane protein that protects against AKI." (PMID 40362229, 2025). "(2019) observed a decrease in blood pressure in db/db mice by exogenous injection of recombinant Klotho protein, suggesting that Klotho may play a regulatory role in diabetes-related hypertension by improving renin-angiotensin system (RAAS) activity or vasomotor function." (PMID 41438297, 2025). "In addition, Klotho has been shown to play an important role in glucose metabolism and may benefit the treatment of diabetes and metabolic syndrome." (PMID 40894259, 2025). "We found a significant inverse association between higher SII values and lower Klotho concentrations in serum, and the association was not affected by age, sex, race/ethnicity, BMI, diabetes, CKD, hypertension, COPD, CHD, or hyperlipidaemia (all P for interaction ≥ 0.05)." (PMID 38169796, 2024). "In this study, we examined the correlation between apoB and Klotho while considering a range of potential confounding factors, including gender, age, race, education level, ratio of family income to poverty, hypertension, high cholesterol level, BMI, diabetes, drinking, smoking, and cancer." (PMID 37352065, 2023). "Furthermore, in subjects with type 1 diabetes mellitus and preserved kidney function, the association of Klotho with vascular disease was reported to be absent for arterial calcification and to be positive for subclinical carotid vascular disease." (PMID 37686263, 2023). "Moreover, the positive impact of Klotho on obesity, diabetes, hypertension, arteriosclerosis, renal and liver function, metabolic homeostasis, and gut microbiota could contribute to its hypolipidemic effects." (PMID 37641103, 2023). "In humans, the levels of Klotho progressively decrease with age, being part of the progressive age-associated loss of kidney functions, and drastic reductions have been associated with many aging-related diseases, such as CKD, hypertension, cancer, diabetes, and cardiovascular disease." (PMID 36829798, 2023). "Thus, we surmise that attenuation of VC by MR409 may be through upregulation of Klotho, which inhibits ROS and Runx2-mediated osteogenic transdifferentiation of VSMCs in diabetes." (PMID 36742073, 2023). "This raises the question of whether Klotho is an appropriate agent to treat diabetes." (PMID 35903083, 2022). "However, the relationship between serum Klotho levels and diabetes remains poorly understood." (PMID 36440221, 2022). "Finally, subgroup analysis stratified by diabetes mellitus were performed and interaction terms on diabetes and Klotho on CKD were investigated, because Previous studies have suggested that Klotho deficiency is associated with the rapid progression of renal function decline in diabetic patients." (PMID 36276390, 2022). "In addition to diabetes, Klotho has been found to have role in obesity." (PMID 35903083, 2022). "However, it should be noted that Klotho expression was not changed in our short-term diabetes model of 10 weeks, suggesting that the loss of Klotho occurs later in DKD disease progression." (PMID 36434087, 2022). "Therefore, preclinical data on Klotho have shown its potential usefulness as an early biomarker for DN development and its progression, and a possible, safe and effective agent in ameliorating diabetic kidney function." (PMID 33478014, 2021). "Therefore, Klotho concentration may be considered as a prognostic factor in the development of chronic complications of diabetes, especially diabetic nephropathy." (PMID 34603200, 2021). "Hence, it could be assumed that Klotho concentration might be a prognostic factor of microangiopathic complications of diabetes." (PMID 34603200, 2021).
diabetes (continued). "The significant effect of Klotho was also independent of traditional risk factors for retinopathy progression (e.g. systolic and diastolic blood pressure measures, HbA1c, duration of diabetes) in multivariable analyses." (PMID 33225726, 2020). "Recent papers have inferred that reduced levels of Klotho correlated with emergence of soft tissue calcifications, cardiovascular diseases, senescence, cancers, chronic hypertension, osteoporosis, renal failure, diabetes mellitus, oxidative stress and uremic parathyroid hyperplasia." (PMID 27759760, 2017). "In conclusion, the present study demonstrated that exogenous rAAV.mKL transfection in DM rats upregulated the expression of klotho and delayed the progression of renal hypertrophy and fibrosis induced by diabetes." (PMID 25695625, 2015). "However, whether the overexpression of the klotho gene inhibits diabetes-induced renal hypertrophy through inhibition of the IGF-1 signaling pathway remains to be elucidated." (PMID 25695625, 2015). "Finally, this review explores the potential of Klotho as both a biomarker and therapeutic target, and outlines future research directions focusing on standardization, mechanistic studies, and translational applications to advance precision medicine in diabetes management." (PMID 41438297, 2025). "The results showed that higher sKlotho levels were positively correlated with the prevalence of type 2 diabetes mellitus (T2DM), a finding that is counterintuitive given the traditional view of Klotho as a protective factor." (PMID 41438297, 2025). "This study provides valuable insights into the role of macrophage depletion in combating diabetes-accelerated kidney senescence through modulation of the GDF-15 and Klotho signaling pathways." (PMID 40362229, 2025). "Previous studies revealed that ER stress, Klotho, and apoptosis appear to be involved in the pathogenesis of AKI-diabetes comorbidity as well as in increased proinflammatory pathways activated and neutrophil infiltration in the diabetic IRI model." (PMID 39656542, 2024). "The serum levels of Klotho have been shown to decrease with certain diseases, including CKD, neurodegenerative conditions, diabetes mellitus and aging." (PMID 38213484, 2024). "In addition, in diabetes the activity of the Wnt pathway could be modulated by the Klotho levels." (PMID 36982322, 2023). "The Klotho-FGF endocrine system holds significant importance in the development of age-related illnesses such as hypertension, diabetes, chronic kidney disease, arteriosclerosis, and cancer." (PMID 37641103, 2023). "Our investigations revealed that common SGLT2 inhibitors used in the treatment of patients with diabetes, CKD, or heart failure modify αKlotho gene expression and Klotho protein secretion in renal MDCK and HK-2 cells." (PMID 36967770, 2023). "Significant variations were noted in age, gender, ethnicity, smoking and drinking habits, healthy eating index, eGFR, SII, medication use, and history of hypertension, diabetes, CHF, CHD, and cancer among the S-Klotho tertiles." (PMID 37821820, 2023). "The levels of Klotho in serum and kidney tissues are decreased in the elderly, as well as in AKI, CKD, diabetes and cardiovascular disease patients with diverse etiologies." (PMID 38239193, 2023). "In db/db mice, KL overexpression inhibited TRPC6 expression and attenuated diabetes-induced podocyte injury, which was accompanied by decreased albuminuria and ameliorated glomerulosclerosis." (PMID 35480629, 2022). "Soluble Klotho could inhibit the PI3K/AKT/mTORC1 signaling to upregulate peroxisome proliferator-activated receptor α (PPARα) expression by directly interacting with type 1 insulin-like growth factor (IGF1) receptor in high fat diet-fed type 2 diabetes mellitus mice." (PMID 35053218, 2022). "The present review examines the role of Klotho in regulating autophagy in Alzheimer’s disease, kidney injury, cancer, COPD, vascular disease, muscular dystrophy and diabetes." (PMID 34737707, 2021).